VCAM1 (vascular cell adhesion molecule 1)
Diseases named in the same sentence as VCAM1 in open-access papers (continued):
Sharing a sentence is not in itself a finding about the gene and the disease.
tumor (continued). "Therefore, the expression of VCAM-1 on tumor lymphatics could lead to increased interaction with cancer cells and further facilitate metastasis." (PMID 22481918, 2012). "Furthermore, chimeric proteins, consisting of antibodies against the tumor vessel marker vascular cell adhesion molecule 1 (VCAM-1), fused to soluble Tissue Factor, induced tumor specific blood clotting, tumor necrosis and growth delay in different xenograft models." (PMID 19703316, 2009). "By modulating the expression of downstream targets such as vascular cell adhesion molecule 1 (VCAM1), lactylation drives tumor cell proliferation, EMT, and metastasis." (PMID 41152975, 2025). "In our study, preoperative blood and tumor levels of VCAM-1 and ICAM-1 were lower in high SCS patients compared to low-medium SCS cases, while VCAM-1 levels in ascitic fluid were elevated in high SCS patients." (PMID 40652770, 2025). "In tumour tissues, PAK1KO increased the expression of ICAM-1 and VCAM-1 by approximately fourfold and fiftyfold, respectively." (PMID 41228228, 2025). "Tumor cells adhere to endothelial surfaces through adhesion molecules such as E-selectin, ICAM-1, and vascular cell adhesion molecule 1 (VCAM-1), facilitating both intravasation and extravasation." (PMID 39940643, 2025). "It promotes the recruitment of T‐cells to inflammatory and tumor sites by enhancing their adhesion via ICAM‐1 and VCAM‐1 and modulating T‐cell activity through VEGFR‐1." (PMID 40944395, 2025). "VCAM-1 and ICAM-1 mediate tumor cell adhesion to endothelial cells and the extracellular matrix, playing key roles in tumor progression, metastasis, and inflammation." (PMID 40652770, 2025). "The expression of VCAM-1 is closely related to angiogenesis and VEGF secretion by tumor cells although their relative influence to each other remains complex." (PMID 40071851, 2025). "VCAM-1-mediated cell adhesion and transmigration is a well-established functional overlap, facilitating immune cell recruitment in IBD and tumour cell metastasis in CRC." (PMID 40095109, 2025). "For example, it can normalize tumor vasculature, improve oxygenation, and upregulate ICAM-1 and VCAM-1, facilitating CAR cell entry into the tumor." (PMID 40722155, 2025). "Here we identified that MMP9, MMP13, VCAM1, and PTX3 overexpression not only promotes ECM remodelling and angiogenesis but also facilitates tumour infiltration, thereby reconfiguring the TME to favour migration and metastasis." (PMID 41007296, 2025). "The observed increase in T-cell and dendritic cell activation, along with promoted vascular normalisation in PAK1KO and PAK4KO tumours, was accompanied by elevated expression of ICAM-1 and VCAM-1." (PMID 40943273, 2025). "This review thereby details the adhesive mechanisms of VCAM-1 in colorectal disease—specifically, driving immune cell infiltration during IBD and tumour cell metastasis in CRC—and posits the potential of this receptor as a common drug target for both diseases." (PMID 40095109, 2025). "VCAM-1 was expressed in 0.9% of CD3+ T cells overall, and in tumour and stromal compartments in 0.4% (range 0.1–7.4%) and 1.0% (range 0.1–8.1%) of CD3+ T cells respectively." (PMID 39792888, 2025). "Spatial transcriptomics revealed SOX18 enrichment at tumor cores and invasive borders, co-localizing with MEF2C, VCAM1, and p-STAT3 in vascular and stromal niches, while SOX30 expression remained low across all tumor regions." (PMID 41373817, 2025). "The enriched expression of STAT3, VCAM1, and MEF2C at the tumor core and invasive front underscores their role in shaping the tumor–stroma interface." (PMID 41373817, 2025). "Our previous work identified VCAM1 was 1 of the top 2 enriched genes (along with ICAM1 and the stemness signature) in the lung metastases of PDXs compared with primary tumor cells." (PMID 40955669, 2025). "Similar phenomena were observed in glioblastoma where exposure to IL-1β induced the expression of VCAM-1 and ICAM-1 on tumor cells." (PMID 40071851, 2025).
tumor (continued). "This process upregulates cell adhesion molecules (ICAM-1 and VCAM-1), the death receptor Fas, and MHC I and II, thereby enhancing the recruitment and activation of innate immune cells and tumor-specific lymphocytes." (PMID 39941843, 2025). "Tumor cells exploit LSECs through adhesion molecules such as intercellular adhesion molecule-1 (ICAM-1) and vascular cell adhesion protein-1 (VCAM-1), aiding liver colonization." (PMID 40563628, 2025). "In a mechanism resembling VCAM-1-mediated leukocyte-endothelial cell attachment, VCAM-1-expressing tumour cells have previously demonstrated a tendency to adhere to cognate α4-expressing leukocytes, such as monocytes and tumour-associated macrophages." (PMID 40095109, 2025). "VEGF and FGF2 induce endothelial anergy by suppressing vascular cell adhesion molecule 1 (VCAM‐1) and intercellular adhesion molecule 1 (ICAM‐1) expression, impairing leukocyte extravasation as well as tumour immune surveillance." (PMID 40268524, 2025). "While ICAM1 and VCAM1 are also expressed outside the vasculature (e.g., by cancer-associated fibroblasts and myeloid cells), the vascular selectins are exclusively expressed by endothelial cells and (for P-selectin) platelets, but not on tumor cells or other stromal populations." (PMID 40796746, 2025). "Adhesion molecules: CAFs can interact directly with tumor cells via adhesion molecules such as N-cadherin, ICAM-1, VCAM-1, etc. and send inhibitory signals to TILs, dampening their cytotoxic responses." (PMID 40805183, 2025). "Conversely, we identified that tumours with low ratios enrich inflammatory/ECM-disrupting genes, such as IL6R, VCAM1, and MMP13, which collectively drive immune suppression and metastasis, in accordance with a poor prognosis and increased invasiveness." (PMID 41007296, 2025). "Other tumor cells express integrin α4β1, mediating direct binding between tumor cells, bone matrix cells, and vascular cells through intercellular adhesion molecule-1 (ICAM-1) and vascular cell adhesion molecule 1 (VCAM-1)." (PMID 38243240, 2024). "Tumor endothelial cells altered glycosylation of ICAM-1, VCAM-1, and PECAM, and lectins, promoting tumor progression and metastasis, and modifying the adhesive properties of endothelial cells." (PMID 39035739, 2024). "Meanwhile, VCAM1 and VEGFA were specifically expressed in cells of cluster EC2 and those of cell state 2, indicating that they were tumor cells." (PMID 39301023, 2024). "According to the flow cytometry analysis of tumor tissue, a significant increase in CD31 + VCAM-1 + cells was observed in the TU2218-administered group, and a significant increase in CD8 + T cells was observed in the anti-PD1 and TU2218-administered group." (PMID 39105882, 2024). "When mouse CD8 T cells were co-cultured with MC38 tumor cells in vitro, they reduced CDC42 expression, and antibodies against VCAM1 or CD49d partially restored their CDC42 expression." (PMID 38332012, 2024). "Tumor ECs undergo genetic alteration, often with downregulated adhesion proteins, such as intercellular adhesion molecule 1 (ICAM-1) and vascular cell adhesion molecule 1 (VCAM-1) that are necessary for immune cell attachment and extravasation." (PMID 38580870, 2024). "Tumor cells, especially CTCs and cancer cells in early metastasis, can acquire genetic alterations to express ICAM-1 and VCAM-1, which enable both attraction and retention of myeloid cells." (PMID 38786066, 2024). "The mechanism of tumor reduction was confirmed by flow cytometry, which showed upregulated VCAM-1 expression in vascular cells and increased influx of CD8 + CTLs into the tumor." (PMID 39105882, 2024). "The accumulation of VEGF within the tumor inhibits ICAM-1 and VCAM-1 expression on endothelial cells, potentially impeding immune cell infiltration." (PMID 38541124, 2024).
tumor (continued). "Treatment with an agonist of CD137 (expressed on tumor endothelial cells) monoclonal antibody increases the expression of ICAM-1, VCAM-1, and E-selectin on tumor endothelial cell surface promoting CD8+ T cells recruitment." (PMID 39325128, 2024). "We showed that MC38 tumor cells downregulated CDC42 expression in iNKT cells in vitro, and that was restored by antibodies against either VCAM1 or CD49d." (PMID 38332012, 2024). "The tumor-associated EC altered glycosylation of surface adhesion molecules including ICAM-1, VCAM-1, and PECAM, and glycan-binding proteins (lectins) also promote tumor progression and metastasis by modifying the adhesive properties of ECs." (PMID 38426109, 2024). "VEGF has been shown to impair leukocyte‐endothelial interactions by reducing the adhesion molecules, ICAM‐1, VCAM‐1, and LFA‐1, in angiogenic vessels and hampering the infiltration of T‐effector cells into tumours." (PMID 38602256, 2024). "Previous studies have confirmed that vascular endothelial cells could secrete adhesion molecules (such as VCAM-1) and induce the accumulation of chemokines on the surface of vascular endothelial cells in the inflammatory response, thereby driving T cells to infiltrate into tumor tissues." (PMID 38671318, 2024). "VCAM‐1 and ICAM‐1 play critical roles in cell adhesion to the endothelium and tumour development, cell proliferation, invasion and angiogenesis." (PMID 37082943, 2023). "Tumor endothelial cells (ECs) promote the adhesion of tumor cells to vascular ECs and inhibit the infiltration of T cells into the tumor bed by modulating CAMs (ICAM‐1 and VCAM‐1)." (PMID 37638340, 2023). "The α4 integrin is a protein located on the surface of Mø, which can recognize the vascular cell adhesion molecule 1 (VCAM-1) on the surface of cancer cells, so it also has tumor-targeting ability." (PMID 37128288, 2023). "Further, histological analysis showed marked endothelial VCAM‐1 expression at the margins of the tumours, and single MPIO bound to VCAM‐1 positive blood vessels." (PMID 37038086, 2023). "VEGF is the major cytokine driving neo-angiogenesis; it decreases the expression of intercellular adhesion molecule (ICAM-1) and vascular cell adhesion molecule 1 (VCAM-1), thus limiting the adhesion and infiltration of immune cells to and into the tumour." (PMID 38136335, 2023). "Tumor endothelial cells act as a major barrier for the extravasation of effector T lymphocytes into the tumor niche through the downregulation of ICAM1 and VCAM1." (PMID 37056346, 2023). "Tumor endothelial cells also show reduced expression of leukocyte binding molecules, including ICAM-1 and 2, VCAM-1, E-selectin and CD34, leading to reduced response to inflammatory signals and defective recruitment of immune cells." (PMID 37234993, 2023). "It is also known that PI3K-AKT-mTOR signaling pathway activation via CAF-derived secretion, such as through CXCL12, VCAM1, IL-22, CXCL5, HGF, and SPARC, induces tumor proliferation, migration, and stemness." (PMID 37264057, 2023). "The effect of Nano-reshaper on the structure of tumor blood vessels was determined using CD31, ICAM-1, and VCAM-1 as the markers." (PMID 36702831, 2023). "Five or seven days after transplantation, we found that these injected monocytes expressed substantial levels of both Trem2 as well as the tumor-specific SCAM marker, Vcam1, compared to the monocytes before injection." (PMID 37164949, 2023). "The vascular cell adhesion molecule-1 (VCAM-1) expressed on the endothelial cell surface promotes interactions between the endothelium and tumor cells, as well as leukocytes." (PMID 37773178, 2023). "Research shows that the tumor endothelium downregulates the expression of endothelial adhesion molecules (EAM) such as ICAM1/2, VCAM1, E-selectin, and CD34." (PMID 37056346, 2023).
tumor (continued). "In the analysis of Western Blot(WB) of tumor tissue,VCAM1,p-STAT3 and PD-L1 in NII.clusterB-PNI were up-regulate than that in other subtypes.In addition,we successfully constructed VCAM1 shRNA cell models of the GC cell lines SNU-216,NCC-24,HGC-27,SNU-1." (PMID 37563649, 2023). "Western blot analysis revealed that both ANL and AS treatments elicited higher levels of vascular cell adhesion molecule-1 (VCAM-1) and intracellular adhesion molecule-1 (ICAM-1) in tumor tissue, especially on the surface of CD31+ tumor vascular cells." (PMID 37620331, 2023). "On blood vessels, RT induces an increase in the production of the integrins ICAM-1 and VCAM-1 in vascular endothelial cells and promotes the transition of CART cells across the vascular endothelium into the tumor tissue." (PMID 37623511, 2023). "Currently, the specific functional role of VCAM1 in RCC is less explored, with data pointing towards its overexpression involving in RCC tumor immune evasion." (PMID 37622107, 2023). "Vascular cell adhesion molecule 1 (VCAM1) and vascular adhesion protein 1 (VAP1) also recruit macrophages by expressing tissue factor, which results in blood clotting and facilitates tumor cell survival." (PMID 36770654, 2023). "Some of these adhesion molecules involved in either weak or strong adhesion between tumor cells and endothelium, such as CD44, VCAM1, and VLA4, play indispensable roles in metastasis." (PMID 37108248, 2023). "Through the deregulation of ICAM-1 and vascular cell adhesion protein 1 (VCAM-1), VEGF-A can also lessen the adhesion between lymphocytes and tumor vascular endothelial cells, which in turn reduces TIL penetration." (PMID 37298230, 2023). "Furthermore, it was proposed that murine pulmonary metastatic progression could be facilitated through the IL-17-dependent induction of VCAM-1 expression on lung endothelial cells, which correlated with altered vessel permeability and enhanced transendothelial migration of tumor cells." (PMID 37234993, 2023). "Conversely, VCAM-1 in PAAD cells was able to produce more lactate by promoting aerobic glycolysis, thereby inducing the macrophages which from the tumor microenvironment to polarize toward M2 macrophages." (PMID 37662928, 2023). "VEGF-A inhibits the release of inter-endothelial and vascular cell adhesion molecules (ICAM-1, VCAM-1) and hinders the migration of CART cells across the vascular endothelial cell barrier into the tumor tissue." (PMID 37623511, 2023). "Adhesive molecules such as VCAM-1, E-selectin, ICAM-1, and VLA-4 are produced by tumor cells during extravasation to facilitate contact between the tumor and the BBB." (PMID 37818447, 2023). "It was well known that LTA stimulates the expression of vascular cell-adhesion molecule 1 (VCAM 1) on vascular endothelial cells and attracts natural killer (NK) cells to parenchymal organs and tumor lesions." (PMID 36929286, 2023). "Our in vitro experiments demonstrated that NAC treatment also affect endothelial function reducing tumor cell transmigration through endothelial monolayers, VCAM-1 traffic to the plasma membrane and VCAM-1 S-nitrosylation." (PMID 37773178, 2023). "TECs are stimulated to express more vascular cell adhesion molecule-1 (VCAM-1) by combined blockade of vascular endothelial growth factor A (VEGFA) and ANG2, which allows anti-tumor T cells to accumulate within various types of tumors in mice." (PMID 37666809, 2023). "It has been reported that the vascular cell adhesion molecule-1 (VCAM-1) is highly expressed on the surface of tumor cells and plays an essential role in the metastasis of tumor cells." (PMID 36839671, 2023). "Inhibition of nSMase2 decreased the expression of VCAM1, CX3CL1, and CXCL10 by ECs and reduced T cell tumor infiltration." (PMID 36901858, 2023). "NEs can bind to circulating tumor cells or inflammatory endothelial cells through ligand receptor interactions, such as CD44 and L-selectin, LFA-1 and ICAM-1, and β 1 integrin and VCAM-1." (PMID 37128288, 2023).
tumor (continued). "Furthermore, ICAM-1 and vascular cell adhesion molecule-1 (VCAM-1) expressed on the BE bind to lymphocyte function-associated antigen 1 (LFA-1, also known as integrin αLβ2) and very late antigen-4 (VLA-4, also known as integrin α4β1) expressed on tumor cells, respectively." (PMID 37190188, 2023). "The Mes tumor subtype predominantly expresses fibroblastic/mesenchymal genes, such as PDGFRA, VCAM1, ZEB1, TWIST1; and extracellular matrix genes, including collagen and FN1 (bolded genes are overlapping with our negative prognostic signature)." (PMID 36555638, 2022). "Neutrophil-derived vesicles have been shown to target tumor cells and inflammatory endothelium through three pairs of interactions including LFA-1/ICAM-1, β1 integrin/VCAM-1, and CD44/L-selectin." (PMID 35874757, 2022). "VEGF has been reported to exert immunosuppressive activity through the following mechanisms: Inhibition of DC maturation, accumulation of MDSCs in tumor, and decreases of ICAM-1 and VCAM-1 in vascular endothelial cells." (PMID 34958105, 2022). "For VCAM1, EGFR and CD24 our findings were validated with healthy and tumor tissue data obtained from the Human Protein Atlas." (PMID 36221114, 2022). "Among them, vascular cell adhesion molecule-1 (VCAM-1), which was reported to augment tumor immune evasion and found dominantly expressed in CAFs 22, 23, ranked as one of the top cytokines down-regulated by FGFRi." (PMID 35832090, 2022). "As demonstrated in our findings, the αD/β2 integrin-VCAM-1 interaction between TAPLT and the endothelium regulates endothelial permeability, thereby impacting on transendothelial migration of tumor cells." (PMID 35408794, 2022). "Radiation induces increased expression of vascular cell adhesion molecule 1 (VCAM-1) and intercellular adhesion molecule 1 (ICAM1) in tumor vessels, thereby promoting tumor infiltration by T lymphocytes." (PMID 36713375, 2022). "Serial sections were used to spatially interrogate antigen expression of vimentin, VCAM-1, CD31, Ki67, nestin, and SOX2 in both tumor cells and the adjacent stroma, specifically at the tumor core, tumor rim, and contralateral striatum." (PMID 35312755, 2022). "HECTD3 depletion downregulates expression of adhesion molecules, such as VCAM-1, ICAM-1 and E-selectin, in mouse primary ECs and HUVECs stimulated by inflammatory factors and inhibits adhesion of tumor cells to ECs both in vitro and in vivo." (PMID 35918322, 2022). "Several genes coding for cell adhesion molecules (CAMs), which are involved in tumor angiogenesis (i.e., ICAM1, PECAM1, and VCAM1), were highly expressed by OERCs of MCC cells—especially MCC14/2." (PMID 35205840, 2022). "The median plasma VCAM-1 levels were significantly higher for the patients with adverse pathologic features such as LNM and advanced pathologic tumor stage (p < 0.05)." (PMID 35347517, 2022). "Finally, we inhibited expression of E-selectin, ICAM-1 and VCAM-1 using a siRNA mixture of siE-selectin, siICAM-1 and siVCAM-1, which blocked upregulation of expression of these adhesion molecules, as well as the increase in tumor cell adhesion induced by HECTD3 overexpression in HUVECs." (PMID 35918322, 2022). "The involvement of VCAM-1 in TAPLT-mediated suppression of endothelial angiogenesis and permeability presents a new avenue of therapeutic approaches against tumor metastasis." (PMID 35408794, 2022). "The endothelial protection and anti-tumor activity of the particular subset of platelets facilitated through engagement of VCAM-1; neutralization of VCAM-1 couple ligand by competitive VCAM-1 abrogated the anti-tumor activity of these platelets." (PMID 35408794, 2022). "Vascular cell adhesion molecule 1 (VCAM1) and glypican-3 are highly expressed on tumor cells and bind to neutrophils." (PMID 36060811, 2022).